KRAS (KRas proto-oncogene, GTPase)
Diseases named in the same sentence as KRAS in open-access papers (continued):
Sharing a sentence is not in itself a finding about the gene and the disease.
tumor (continued). "Indeed, the suppression of extracellularly-derived fatty acid activation is sufficient to trigger anti-tumor effects in KRAS-driven lung cancer." (PMID 31344914, 2019). "From the group of 12 patients with KRAS mutation found in tumor, only one had negative EBC (a false negative)." (PMID 30368666, 2019). "In addition, ultra-deep sequencing identified KRAS mutations in 17 cases where tumour tissue was deemed insufficient for genotyping, suggesting that ultra-deep targeted sequencing of cfDNA may be instrumental for the identification of specific SGAs in cfDNA missed in tumour tissue." (PMID 31817150, 2019). "No mutation in the 13 other genes covered by the TruSight Tumor 15 gene panel was observed in any case, except for the BRAF mutation detected in the single primary tumor being KRAS-negative." (PMID 30611220, 2019). "EMT in tumor cells can also be induced by cellular stress such as inflammation or nutrient/oxygen deprivation, and transforming oncogenes including oncogenic KRAS." (PMID 31681587, 2019). "Additionally, 48% of the patients had emergence of new KRAS and NRAS mutations at disease progression, showcasing tumor heterogeneity." (PMID 31824558, 2019). "These consequences verified miR‐193a‐3p as a tumor suppressor, whose impact could be reversed by oncogenic KRAS, which further verified the preceding validation of miR‐193a‐3p/KRAS control in this article." (PMID 30575330, 2019). "And these results further verified that both the KRAS status and location of tumor could affect the treatment effectiveness and prognosis in CRC patients." (PMID 30917791, 2019). "For KRAS mutations with frequency ≥1%, the concordance between tumor center and invasion front and between primary tumor and metastasis was 94.7% and 90.9%, respectively, implying the absence of heterogeneity in KRAS mutations." (PMID 31891652, 2019). "Among the nine patients with non-metastatic CRC bearing tumor-associated KRAS mutations, the diagnostic sensitivity after enrichment assay was significantly higher than that before the enrichment assay (88.9% vs. 11.1%, P < 0.01)." (PMID 31383871, 2019). "More specifically, acinar cells lacking PTF1A are more frequently transformed by KRAS, while NR5A2 prevents KRAS induced neoplasia through the maintenance of acinar cell plasticity, and PDAC metastasis has been observed to increase with the activation of KRAS and the expression of c-Myc TFs." (PMID 31772762, 2019). "However, it is not well-known how these individual RAF kinases contribute to KRAS-mutant tumor initiation and development." (PMID 31612108, 2019). "This is partially because the detection methods at present are limited to detect the very low amount of ctDNAs in early stage of cancer patients, and some mutations such as KRAS are not specific for certain types of tumour but exist in many tumour types." (PMID 30873683, 2019). "Within KRAS exon 2, the distribution of mutations was not significantly different according to tumour type assuming low numbers." (PMID 30837681, 2019). "There was only 64% concordance for KRAS mutation presence between tumour tissue and plasma samples where KRAS mutations were reported in the tumour but not in the plasma samples." (PMID 30585255, 2019). "KRAS, NRAS or BRAF mutations had been identified in tumour samples from sixteen of the twenty-four patients (75%), and in twelve of these (75%) the mutation could be verified in the pre-treatment plasma sample by ddPCR." (PMID 31395942, 2019). "Therefore, we stained sections of paraffin embedded tumor samples for their KRAS and PIK3CA expression." (PMID 30001368, 2018). "Moreover, our analysis identifies consistent cross-cancer effects for 4 genes (FGFR1, ERRB2, IDH1, KRAS/NRAS) in 11 histological tumor types." (PMID 30442178, 2018).
tumor (continued). "Thus, it is important to determine the genotype (such as KRas status) of the tumor cells, not only the phenotype of GLUTs upregulated in the cells under investigation." (PMID 30205572, 2018). "However, RAS mutational status is not the sole determinant of functional synergism between RAF and MEK inhibitors, as demonstrated in KRAS isogenic tumor cell line models." (PMID 29986755, 2018). "Since NF-kB regulates multiple anti-apoptotic genes and is considered to be a major contributor to radioresistance, it is possible that simultaneous mutations in KRAS and SMAD4 (as observed in the present study) contributed to the radioresistant nature of the tumor via this mechanism." (PMID 30220971, 2018). "Indeed, mitophagy has been involved in KRAS-induced transformation to overcome an energy deficit in tumor cells and is also required for benign hepatic tumors to progress into malignant hepatocellular carcinoma." (PMID 29971063, 2018). "Similar sensitivity was observed when recombinant free and ARS-1620-bound KRASG12C protein was spiked into lysate from a resected human tumor sample that did not harbor a KRAS mutation." (PMID 30254226, 2018). "With respect to the optimal tissue used for testing, samples from the primary tumor and the metastatic site have shown good concordance for KRAS mutations, but evidence does not support reliable concordance rates for lymph node metastases or recurrent tumors." (PMID 30519549, 2018). "Our previous results suggested that KRAS accelerates tumor formation by modulating the tumor microenvironment (TME) and favoring peritoneal dissemination through production of granulocyte macrophage colony-stimulating factor, followed by neutrophil infiltration." (PMID 30509235, 2018). "Furthermore, around 50% of cases showed KRAS and/or NRAS mutations for each category of tumor cell content (27/54 in cases with <10% tumor cell content; 278/553 in those with 10–50% tumor cells; or 59/117 in cases with >50% tumor cells)." (PMID 29755687, 2018). "Due to genomic instability, it is reasonable to speculate that for many genes other than KRAS the genomic profile of metastases may show a greater deviation from the profile of the primary tumour." (PMID 30029640, 2018). "Furthermore, treatment of KRAS or EGFR mutant‐driven transgenic LUAD mouse models revealed that cell growth arrest induced by the HCI‐2509 inhibitor resulted in both lower tumor formation and progression in vivo." (PMID 30220105, 2018). "In particular, one patient with KRAS and NRAS wild-type who initially responded to chemotherapy plus cetuximab but that successively progressed, evidenced a K57 T MEK1 mutation in the NGS analysis of the primary tumour and liver metastasis." (PMID 29534749, 2018). "Thus, mutant KRAS-specific T cells residing within tumor lesions can elicit clinically beneficial effects if the matching mutant KRAS epitope is naturally processed and presented." (PMID 30283732, 2018). "We hypothesize that consistent with a starvation-insensitive feature of tumor cells, constitutively activated KRAS could prevent nucleolar accumulation of calpain-2 and therefore ribosomal biogenesis might proceed even in the absence of serum." (PMID 29507677, 2018). "In support of these proposals, HIF-2α, but not HIF-1α deletion, has been shown to increase tumor growth and progression secondary to loss of the tumor suppressor secretoglobin 3a1 protein in a KRAS-driven lung tumor model." (PMID 29784889, 2018). "Oncogenic KRAS has been shown to be a key factor in promoting metabolic rewiring, although the specific metabolic actors may differ depending on tumour type and genetic context." (PMID 30514331, 2018). "Moreover, our analysis identifies consistent cross-cancer effects for 4 genes (FGFR1, ERRB2, IDH1, KRAS/NRAS) in 14 tumor types." (PMID 30442178, 2018).
tumor (continued). "The examined liver metastasis in this patient had 79% shared mutations with the primary tumour harbouring the KRAS c.38G > A mutation, while no mutations were shared with the other primary tumour." (PMID 30029640, 2018). "Should LGR5 also regulate MEK/ERK signalling in CRC cells, this could alter tumour behaviour substantially, particularly during the stages of CRC development where a KRAS mutation (which constitutively activates MAPK signalling) has not yet been accrued." (PMID 29844449, 2018). "KRAS mutation was associated with better outcomes of PD1/PD-L1 blockade, which is consistent with the observed correlation of KRAS mutation with higher PD-L1 expression in tumor specimens." (PMID 29484144, 2018). "KRAS mutations in the tumor are a negative predictor of response to EGFR-TKIs or anti-EGFR antibodies." (PMID 29441349, 2018). "Furthermore, KRAS-driven NF-κB activation has been associated with feedforward amplification of RAS signalling, drug resistance, and tumour stemness." (PMID 30142927, 2018). "In addition, amplification of PIK3CA and FGFR2 in T2 and T3, combined with activating mutations in KRAS and PIK3CA in T1−3, indicates a critical role for the RAS-PI3K axis in tumor survival through multiple rounds of radiotherapy." (PMID 30220971, 2018). "Highly sensitive detection methods should be preferred to avoid false-negative results, as even small fractions of KRAS mutated tumor cells have been shown to permit the development of secondary-resistance shortly after treatment initiation." (PMID 30234115, 2018). "Patient 41 tumor tissues harbored KRAS wild-type and showed no mutations in the blood during treatments." (PMID 29849949, 2018). "To identify the MPE effectors and transcriptional signatures of IL-1β/KRAS/IKKα-addicted tumor cells, we subjected KRAS-silenced, IKKα-silenced, and IL-1β-challenged LLC and MC38 cells to microarray analyses, seeking for transcripts altered heterodirectionally by silencing/challenge." (PMID 29445180, 2018). "Whether KRAS-mutant tumor growth inhibition in the vitamin C-treated mice was related to markers of oxidative stress in the tumor was not tested." (PMID 30018566, 2018). "Finally, among 35 patients (58.3%) whose tumor KRAS status was determined, 10 patients (16.7%) had tumors with wild-type KRAS, whereas the tumors in 25 (40%) had mutant KRAS." (PMID 29774414, 2018). "The notion that multiple signaling pathways can activate JUN may explain why KRAS mutant tumor cells are traditionally seen as highly refractory to MEK inhibitor therapy." (PMID 30482246, 2018). "Cells could be re‐cultured in 3T3 + Y following recovery of the xenograft tumor and Sanger sequencing demonstrated that these were KRAS mutant." (PMID 29569246, 2018). "DNA samples with the G12C mutation were used because no patients carried the KRAS G12R mutation in tumor tissues." (PMID 29849949, 2018). "KRAS mutations could also have pre-existed in few tumor cells, and have expended due to KRAS-wild-type tumor resistance to cetuximab and panitumumab therapy." (PMID 29707145, 2018). "The potentially tumor-promoting role of PDAC could be outsmarted, particularly if KRAS-directed B cells promote tumor progression upon binding of their BCR to the nominal target antigens and subsequent production of tumorigenic cytokines." (PMID 30283732, 2018).
tumor (continued). "Moreover, it has been demonstrated that miR-216b exerts its tumor suppressor function through the inhibition of the Kirsten rat sarcoma viral oncogene homolog (KRAS)–ERK pathway." (PMID 29535681, 2018). "Oncogene-induced senescence appears to decrease the frequency of the multistep progression in KRAS- or BRAF-mutated adenocarcinoma, whose tumor evolution may be associated with epigenetic alterations and kinase-inactive mutations." (PMID 29690599, 2018). "The analysis of various mutant combinations allowed the determination that the initiating APC and KRAS mutations act as the drivers of proliferation and tumor growth, while inactivating mutations in SMAD4 block differentiation during tumor growth and being required for metastatic potential." (PMID 29652830, 2018). "We and others applied stabilized anti-KRAS esiRNA in vivo and saw a strong decrease in tumor growth, which might be an excellent option to overcome the undruggable state of mutated active KRAS." (PMID 30001368, 2018). "In the KRAS wt tumor-bearing mice two out of ten mice gave a complete response." (PMID 29343688, 2018). "Inconsistent with these results, our study showed that KRAS mutation was associated with mucin production, tumor stage, non-smoking and CRC family history." (PMID 29423347, 2018). "KRAS and EGFR mutations were detected in samples with a minimum of 32% viable tumor cells." (PMID 29673125, 2018). "Perturbing ROS homeostasis or inhibition of NOX1 reduced tumor growth and angiogenesis in vivo and could represent a new possible therapeutic approach in LKB1-deficient KRAS-mutated tumors." (PMID 29915721, 2018). "Furthermore, SB induced caspase-3 activation and PARP cleavage only in MiaPaCa2 but not in A549 cells, suggesting that GSK3α/β inhibition selectively induces apoptosis in mutant KRas-dependent tumor cells." (PMID 30514931, 2018). "The problem is that these patients are good candidates for anti-EGFR antibody treatment because they have no KRAS mutations in tumor tissues before treatment." (PMID 29849949, 2018). "Further investigation of the CTH gene in colorectal carcinogenesis with regards to KRAS and BRAF mutations or other molecular characteristics of the tumor may be warranted." (PMID 29694444, 2018). "The ensemble of molecular studies has provided the recognition of the main somatic genetic lesions occurring in the two main tumor subtypes: thus, EGFR and KRAS mutations and ALK-EML4 fusions mainly occur in adenocarcinomas, while DDR2, FGFR2 and NFE212 mainly occur in squamous cell carcinomas." (PMID 30060526, 2018).
tumor (continued). "Given the fact that alterations in metabolic pathways in KRAS-wt and KRAS-mt may differ in tumor cells with different genetic backgrounds, this may also attribute to differential PI sensitivities in solid tumors." (PMID 29184971, 2018). "Preclinical data suggest that oncogene (EGFR and KRAS) events regulate tumor procoagulant activity." (PMID 29743116, 2018). "Strong IFN-production could be identified in individual TIL preparations against single KRAS mutants or against individual TAAs, e.g. NY-ESO-1 epitopes that was also associated with antigen protein expression in the matching tumor lesion." (PMID 30400835, 2018). "These CSCs showed high sensitivity to OXPHOS inhibitors (preferentially to oligomycin) that, when combined with targeted therapy for the KRAS pathway, could eliminate the tumour and prevent recurrence." (PMID 29991569, 2018). "Paired tumour samples were available in 42 cases and the concordance for KRAS status was 83% (25 KRAS wild-type and 10 KRAS mutant) while in 7 patients KRAS mutation was detected in the pre-treatment biopsy but not in the post-treatment resection specimen." (PMID 29362371, 2018). "A fast orientation of TIL recognizing common targets, including common pathogens, non-mutant tumor associated antigens, as well as mutant tumor driver mutations (e.g. KRAS) aids to define very fast the quality and nature of individual TIL preparations." (PMID 30400835, 2018). "KRAS genotyping in tumor samples is a decisive clinical test for the anti-EGFR therapy management." (PMID 30406144, 2018). "The genetic network connecting JUN and MAPK signaling may explain why KRAS mutant tumor cells are traditionally seen as highly refractory to MEK inhibitor therapy, but these genetic interactions may also provide a therapeutically exploitable vulnerability." (PMID 30482246, 2018). "Multivariate regression showed that CD166 and KRAS exon 2 mutation statuses do not have any correlation to the clinical histopathological factors of the patients which include age, sex, tumor stage, lymph node status, distant metastasis and overall survival." (PMID 29755662, 2018). "Furthermore, active KRAS mutations in colon cancer cells were shown to inhibit the expression of STAT1, allowing them to escape tumor surveillance mechanisms due to reduced responsiveness to IFN-γ." (PMID 30235866, 2018). "This may be possibly due to lower amounts of mutant KRAS protein expressed and subsequent lower antigen turnover in the tumor as compared to NY-ESO-1 expression, which is quite high based on immunohistological studies." (PMID 30283732, 2018). "In addition, the 2 cases with KRAS wild type in primary tumours demonstrated KRAS G12S or G12V in the corresponding ovarian metastasis." (PMID 29662660, 2018). "The over-expression of PD-L1, promoted by oncogenic and constitutively activated signals, including epidermal growth factor receptor (EGFR), protein kinase B (AKT) and Kirsten rat sarcoma viral oncogene homolog (KRAS) pathways, is responsible for an innate (tumor cell intrinsic) resistance." (PMID 30386337, 2018). "RASGAPs should exert a tumor suppressor function in KRAS wild type and not in cells that harbor a mutant KRAS allele." (PMID 29440633, 2018). "In vivo functional screening of a gene library informed by oncogenomics-guided integration of mutant KRAS-specific mouse and human gene signatures reveal several genes whose expression promote tumor growth and/or metastasis, as outlined here and in the companion paper." (PMID 30013058, 2018). "A single KRAS mutation was not confirmed in the validation analysis, most likely due to heterogeneity in the primary tumour." (PMID 30029640, 2018). "There was a significant correlation between KRAS mutations and older ages and tumor type (non-mucinous)." (PMID 30579343, 2018). "Furthermore, a human IgG1 monoclonal antibody interfering with mutant KRAS function inside the cell has been described to inhibit growth of KRAS-mutant xenografts in tumor-bearing mice." (PMID 30283732, 2018).